PIWIL3 (piwi like RNA-mediated gene silencing 3)
Diseases named in the same sentence as PIWIL3 in open-access papers:
PIWIL3 is named in the same sentence as 22 diseases in open-access papers, as found by Europe PMC text mining. Sharing a sentence is not in itself a finding about the gene and the disease. The quoted sentences say what the papers report.
glioma (10 papers, 2019 to 2023). A benign or malignant brain and spinal cord tumor that arises from glial cells (astrocytes, oligodendrocytes, ependymal cells). "PIWIL3 are expressed at low levels in glioma tissues and negatively associate with glioma pathological grade." (PMID 31399034, 2019). "Conversely, PIWIL3 overexpression seems to have a protective effect in glioma cell lines and decreased tumor size in vivo." (PMID 37568728, 2023). "In another study, PIWIL3/OIP5-AS1/miR-367-3p/CEBPA (CCAAT/enhancer binding protein alpha) feedback loop was found to regulate glioma cell growth, and the overexpression of PIWIL3 or piR-30188, either jointly or separately suppressed glioma progression." (PMID 33800703, 2021). "In contrast, PIWIL3 exhibited a protective effect in glioma cells, and low expression of PIWIL4 has been found in tumor cells from hepatocellular carcinoma, breast cancer and non-small cell lung cancer." (PMID 32357464, 2020). "Up-regulation of miR-367-3p, piR-30,188 and PIWIL3 or knockdown of OIP5-AS1 led to suppression of glioma progression." (PMID 33109195, 2020). "In contrast, PIWIL3 seems to play a protective effect due to its overexpression-reduced proliferation, migration and invasion of glioma cells in vitro and decreased tumor size in vivo." (PMID 32357464, 2020). "The PIWIL3/piR-30188/OIP5-AS1/miR-367-3p/CEBPA/TRAF4 pathway can regulate the biological behavior of glioma cells." (PMID 31399034, 2019). "piR-30188 and PIWIL3 expression is decreased and negatively correlates with glioma pathological grade." (PMID 31399034, 2019). "piR-30188/PIWIL3 binds to OIP5-AS1, a cancer-associated lncRNA, a target of miR-367-3p in gliomas." (PMID 37568728, 2023). "In contrast, overexpression of PIWIL3 significantly inhibited the progression of glioma." (PMID 38031146, 2023). "The combination of OIP5-AS1 knockdown with the over-expression of PIWIL3 and miR-367-3p leads to tumor regression, identifying a novel molecular pathway in glioma cells that may provide a potential innovative approach for cancer therapy." (PMID 37568728, 2023). "PiR-598, piR-8041, piR-DQ590027, piR-DQ593109, PIWIL1, PIWIL2, PIWIL3, and PIWIL4 may all be involved in the pathogenesis of glioma, and could be diagnostic markers for glioma." (PMID 33109195, 2020). "Furthermore, piR-30,188 and PIWIL3 expression are decreased and negatively correlated with pathological grade of the glioma." (PMID 33109195, 2020). "Therefore, PIWIL3/piR-30188 regulates the glioma cell malignant phenotype via the OIP5-AS1/miR-367/CEBPA/TRAF4 pathway." (PMID 31399034, 2019). "One study reported that PIWIL3, piR-30,188 and miR-367-3p were decreased and OIP5-AS1 was increased in glioma." (PMID 33109195, 2020). "PIWIL3 plus piR-30,188 and the PIWIL3/OIP5-AS1/miR-367-3p/CEBPA (CCAAT/enhancer-binding protein alpha) complex is involved in the pathogenesis of glioma." (PMID 33109195, 2020). "The tumor-suppressor PIWIL3 has a low expression in glioma and a negative correlation with the pathological grade of the disease." (PMID 38031146, 2023). "The molecular action for PIWIL3 and PLD6 in low grade OC could be involvement in growth regulation such as in glioma and mediating downstream pathways for proto-oncogene, MYC, as seen in breast cancer, respectively." (PMID 33374923, 2020).
breast carcinoma (6 papers, 2012 to 2023). "PIWIL3 is also considered a prognostic biomarker of breast cancer since its upregulation was significantly associated to a short progression-free survival (p = 0.01) and a poor overall survival (p = 0.02)." (PMID 32357464, 2020). "Moreover, PIWIL3 is considered a prognostic biomarker of breast cancer (BC) since its upregulation is significantly associated with poor overall survival." (PMID 37568728, 2023). "In breast cancer, PIWIL1 and PIWIL3 gene expressions were reported to be upregulated, whereas PIWIL2 and PIWIL4 were downregulated compared with normal breast tissue." (PMID 32987715, 2020). "Reports on the clinical significance of PIWIL3 and PIWIL4 remain scarce, and in particular, this is the first study to identify the contribution of PIWIL3 and PIWIL4 genes to breast cancer prognosis." (PMID 27177224, 2016).
gastric cancer (3 papers, 2020 to 2023). A primary or metastatic malignant neoplasm involving the stomach. "In gastric cancer, overexpression of Piwil3 promoted cell proliferation, migration, and invasion via the JAK2/STAT3 signaling pathway." (PMID 34295823, 2021). "In contrast, PIWIL3 had increased expression in more malignant tumors of gastric cancer and melanoma wherein overexpression leads to proliferation and invasion." (PMID 33374923, 2020). "In gastric cancer (GC), PIWIL3 upregulation increases cell proliferation, migration, and invasion." (PMID 37568728, 2023).
pancreatic cancer (3 papers, 2020 to 2022). "We aimed to discover PIWIL3- and PIWIL4-modulated piRNAs and determine their potential mechanisms in pancreatic cancer and the clinical implications." (PMID 36555927, 2022). "PIWIL3 or PIWIL4 was downregulated in pancreatic cancer-derived cell lines or in a non-tumour cell line." (PMID 36555927, 2022). "Finally, PIWIL3 and PIWIL4 evaluation in human pancreatic cancer samples showed that patients with low levels of PIWIL4 protein expression presented poor prognosis." (PMID 32357464, 2020). "In the present study, we evaluated PIWIL1, PIWIL2, PIWIL3 and PIWIL4 expression in pancreatic cancer-derived cell lines and in one non-tumor cell line as healthy control." (PMID 32357464, 2020). "However, PIWIL3’s and PIWIL4’s role in carcinogenesis is rather controversial, and their clinical implication in pancreatic cancer has not yet been investigated." (PMID 32357464, 2020).
malignant melanoma (2 papers, 2019 to 2020). "PIWIL3 protein is also increased in more aggressive primary malignant melanoma and metastatic disease, and thus may be involved in malignant melanoma progression." (PMID 31399034, 2019).
benign ovarian tumors (1 paper, 2014). "In order to investigate a possible role of this pathway in EOC, we performed semi-quantitative RT-PCR to investigate the expression of PIWIL1, PIWIL2, PIWIL3, PIWIL4 and MAEL in advanced stage serous EOC (n = 25), benign ovarian tumors (n = 19) and normal ovarian tissue (n = 8)." (PMID 24932571, 2014).
cervical cancer (1 paper, 2020). A primary or metastatic malignant neoplasm involving the cervix. "Since expression of PIWI proteins increased resistance to drugs in cervical cancer and in non-small cell lung cancer, we decided to evaluate whether PIWIL3 or PIWIL4 were able to modulate chemoresistance of PC." (PMID 32357464, 2020).
diabetes (1 paper, 2016). "However, they are related to diabetes or insulin secretion (rs757110 in ABCC8, rs5215 and rs5219 in KCNJ11), carotid intima media thickness (rs2468844 in SAA2), and oligospermia (rs11703684 in PIWIL3)." (PMID 27900359, 2016).
ductal carcinoma in situ (1 paper, 2020). "PIWIL3 did not present any nuclear or cytoplasmic immunoreactivity in atypical ductal hyperplasia and ductal carcinoma in situ." (PMID 33008024, 2020).
Infertility (1 paper, 2024). "Interestingly, also humans encode a PIWIL3 protein and we identified one female variant carrier with a homozygous LoF variant in TDRD12, diagnosed with infertility due to premature ovarian insufficiency, a phenotype related to impaired oocyte maturation." (PMID 39122675, 2024).
ovarian carcinoma (1 paper, 2022). A malignant neoplasm originating from the surface ovarian epithelium. "Four PIWI proteins i.e., PIWIL1/HIWI, PIWIL2/HILI PIWIL3/HIWI3 and PIWIL4/HIWI2 that have been identified in the prognosis and diagnosis of Ovarian Cancer." (PMID 35715825, 2022).
skin tumors (1 paper, 2020). "PIWIL3 gene had emerging aberrant levels of expression in bladder, endometrial, ovary, lung and liver tumors and was only overexpressed in skin tumors." (PMID 33008024, 2020).
sterility (1 paper, 2023). "In female golden hamsters, PIWIL1 and PIWIL3 are highly expressed throughout oogenesis and early embryogenesis, while knockout of PIWIL1 leads to sterility, and PIWIL3 deficiency results in subfertility with lagging zygotic development." (PMID 37644029, 2023).
cancer (13 papers, 2010 to 2024). A tumor composed of atypical neoplastic, often pleomorphic cells that invade other tissues. "In malignant melanoma, upregulation of Piwil3 was association with cancer aggressiveness and progression." (PMID 34295823, 2021). "This implies that re-expression of PIWIL3 in cancer cells results in repressed RNAi, subsequently promoting cancer cell growth." (PMID 39596284, 2024). "There are four known human PIWI homologs: PIWIL1 (HIWI), PIWIL2 (HILI), PIWIL4 (HIWI2), and PIWIL3 (HIWI3), all of which have been shown to be expressed in a number of different cancer tissues." (PMID 39596284, 2024). "The deregulation of PIWIL3 is reported in many cancer types; it is highly expressed in both primary ovarian cancer (OC) and metastatic tissues." (PMID 37568728, 2023). "Although mostly present in normal testis tissue, PIWIL3 has been reported to be aberrantly expressed in a variety of cancers, playing important roles in tumorigenesis." (PMID 35804828, 2022). "Some studies have reported the expression of these proteins with oncogenic features; e.g., one study described how cancer cells re-express PIWIL3 to promote cancer cell growth." (PMID 32357464, 2020). "PIWIL3 was located both in the nucleus and the cytoplasm of cancer cells with a slight intensity (HScore: 1)." (PMID 33008024, 2020). "On the other hand, PIWIL2 and PIWIL4 show low expression in many normal tissues and are upregulated in several cancer types, while PIWIL3 is almost undetectable in all tissues considered, except germline." (PMID 31694219, 2019). "PIWIL3 is associated with metastasis and proliferation, while PIWIL4 is also observed to have an impact on other processes such as cell cycle, apoptosis, and regulation of cancer immunology." (PMID 39596284, 2024). "In most of malignant tumors belonging to this panel, we observed an expression profile comparable to IBCs associating variable PIWIL2 and PIWIL4 genes downregulation and an emerging aberrant expression of PIWIL1 and PIWIL3." (PMID 33008024, 2020). "Since PIWIL3 and PIWIL4 expression has not been studied in PC and the functions of PIWI proteins in cancer seem to be rather controversial, we have evaluated the role of PIWIL3 and PIWIL4 expression in pancreatic cells and dissect their prognostic potential in PC." (PMID 32357464, 2020). "The four human PIWI proteins PIWIL1, PIWIL2, PIWIL3 and PIWIL4 can be included in the cancer/testis antigens (CTAs) class and their deregulation is involved in cancer cell proliferation, apoptosis and stemness, genomic integrity, invasion and metastasis." (PMID 33008024, 2020). "Other research highlighted that PIWIL3 and PIWIL4 presented oncogenic potential in several types of cancers." (PMID 32357464, 2020). "The human genome encodes four PIWIL genes, known as PIWIL1 (HIWI), PIWIL2 (HILI), PIWIL3 (HIWI3), and PIWIL4 (HIWI2); some of which were found to be highly expressed in several human cancers." (PMID 32204558, 2020). "PIWIL1, PIWIL3, and PIWIL4 act as intrinsic regulators of the self-renewal capacity of germ line and hematopoietic stem cells, and are believed to be involved in cancer development." (PMID 28422722, 2017). "Since PIWIL3 is more abundant in cancer cells, it might in part explain the specificity of ENX towards cancer cells." (PMID 35804828, 2022). "The human PIWI subfamily of Argonaute proteins comprise 4 members, PIWIL1/HIWI, PIWIL2/HILI, PIWIL3 and PIWIL4/HIWI2, all found in testis, although recently a number of reports have identified elevated expression of HIWI and HILI in a variety of human cancers." (PMID 25313140, 2014). "Germinal PIWIL3 protein was not expressed in any malignant tumor belonging to the multitumor panel." (PMID 33008024, 2020).
tumor (10 papers, 2012 to 2023). "In the tumor group showing PIWIL3 emerging expression, significant positive associations were observed with PR- status (p = 0.026), ERBB2-negative status (p = 0.0004) and molecular subtype (p = 0.0017)." (PMID 33008024, 2020). "In contrast, piR-168112 expression was lower in tumour cell lines after PIWIL3 silencing than in the same cell lines transfected with scramble (Log2 fold change = −25.58; adjusted p-value = 6.32 × 10−10)." (PMID 36555927, 2022). "PIWIL3 is expressed in stage III epithelial ovarian cancer in both primary tumor and metastatic tissues compared with their adjacent normal tissues (p < 0.01), and the expression is higher in the metastatic foci." (PMID 32357464, 2020). "PIWIL3 plays an important role in melanoma, and its expression correlates with the tumor stage." (PMID 37568728, 2023). "Finally, piR-162725 was significantly downregulated in the RWP1 tumour cell line after PIWIL3 silencing compared to the same tumour cell line after PIWIL4 silencing (Log2 fold change = −24.44; adjusted p-value = 1.63 × 10−5)." (PMID 36555927, 2022). "Piwil3 showed a tumor-type dependent function as an oncogene or tumor suppressor." (PMID 34295823, 2021). "Interestingly, this fact was not only observed in tumor cell lines but also in the normal cell line, which also decreased its motility after PIWIL3 and/or PIWIL4 downregulation." (PMID 32357464, 2020). "Since PIWIL3 and PIWIL4 are expressed in the immortalized non-tumor pancreatic cell line, we cannot conclude that PIWIL3 or PIWIL4 could act as an oncogene." (PMID 32357464, 2020). "Furthermore, PIWIL3 seems to play a crucial role in melanoma progression, and its expression is higher with the higher tumor stage." (PMID 32357464, 2020). "Furthermore, the expression of piR-168112 was even lower in the normal, untransformed cell line after PIWIL3 silencing compared to tumour cell lines after PIWIL3 silencing, the latter showing higher expression (Log2 fold change = −27.10; adjusted p-value = 7.52 × 10−11)." (PMID 36555927, 2022). "PIWIL3 and piR-30,188 complex bind to carcinoma-related OIP5-AS1 to reduce its expression, reversing its inhibitory effect on its downstream tumor suppressor target miR-367-3p." (PMID 38031146, 2023). "We have also discovered the link between PIWIL3 and PIWIL4 and epithelial-to-mesenchymal transition (EMT) and tumour cell dedifferentiation status and chemoresistance." (PMID 36555927, 2022). "Here, we observed how PIWIL3 and PIWIL4 knockdown decreased motility of both tumor and normal cells through a mesenchymal arrest in favor of the epithelial phenotype." (PMID 32357464, 2020). "On the other hand, PIWIL3 and PIWIL4 showed higher protein levels and a differential expression pattern throughout cell lines, which includes a non-tumor cell line." (PMID 32357464, 2020). "PIWIL1, PIWIL2, PIWIL3 and PIWIL4 were all deregulated with a dissociated profile: PIWIL1 and PIWIL3 had an abnormal emergent expression and the remaining PIWIL2 and PIWIL4 were variably downregulated in tumor tissues at RNA and protein levels." (PMID 33008024, 2020). "Remarkably, we observed that PIWIL3 and/or PIWIL4 knockdown dropped drastically the number and diameter of spheres of tumor cell line RWP1 (p < 0.001)." (PMID 32357464, 2020). "Subsequently, functional experiments with PIWIL3 and/or PIWIL4 knockdown revealed a decrease in the motility ratio of tumor and non-tumor cell lines through downregulation of mesenchymal factors in pro of epithelial factors." (PMID 32357464, 2020). "In contrast, PIWIL3 and PIWIL4 showed overexpression in almost all tumor-derived cell lines, and in the non-tumor pancreatic cell line compared to control." (PMID 32357464, 2020). "Our findings support PIWIL3 and PIWIL4 as crucial factors in the regulation of cell motility, stem cell maintenance and drug resistance both in tumor and healthy pancreatic cells." (PMID 32357464, 2020).
tumor (continued). "Comparison with normal breast tissues revealed that two genes (PIWIL1 and PIWIL3) were up-regulated and the remaining two (PIWIL2 and PIWIL4) were down-regulated in tumor tissues." (PMID 27177224, 2016). "In tumor tissue, PIWIL1 expression was detected in eleven patients (15.5%), PIWIL2 in 66 (93%), PIWIL3 in five (7%) and PIWIL4 in 60 (84.5%)." (PMID 25742785, 2015). "Furthermore, we found a large number of differentially expressed piRNAs when comparing tumour cell lines (RWP1 and PL45) downregulated for PIWIL3 or PIWIL4 against IPMN samples (n = 94) or against human PDAC samples (n = 22)." (PMID 36555927, 2022). "We identified immunostaining of tumor cells with anti-PIWIL1 antibodies in 34,6% of IBCs (n = 52) and anti-PIWIL3 antibodies in 8% of IBCs (n = 12) and absence or slight staining with anti-PIWIL2 antibody in 48,3% of IBCs (n = 67) and anti-PIWIL4 antibody in 48,6% of IBCs (n = 73)." (PMID 33008024, 2020). "Indeed, PIWIL3 and/or PIWIL4 silencing overcame Gemcitabine resistance of the non-tumor cell line (p < 0.001), and significantly increased the other treatment effects (p = 0.003 for Nab-Paclitaxel; p = 0.001 for Gemcitabine + Nab-Paclitaxel)." (PMID 32357464, 2020). "PIWIL3 and PIWIL4 were located both in the nucleus and the cytoplasm of tumor cells." (PMID 33008024, 2020). "Higher PIWIL3 or PIWIL4 downregulation in both tumor cell lines was achieved between the fifth/sixth days compared with the second day obtained in the non-tumor cell line." (PMID 32357464, 2020). "Here, we found that maximum PIWIL3 or PIWIL4 downregulation was achieved later in both tumor cell lines than in non-tumor cell line." (PMID 32357464, 2020). "Therefore, the role of PIWIL3 and PIWIL4 in tumor initiation and development remains still unclear." (PMID 32357464, 2020). "Here, we show a differential expression in tumor and non-tumor cell lines of PIWIL3 and PIWIL4." (PMID 32357464, 2020). "Following with functional experiments with PIWIL3 and/or PIWIL4 downregulation, we evaluated the ability of both tumor and non-tumor pancreatic derived cell lines to form pancreatic spheres in stem cell enrichment culture media." (PMID 32357464, 2020). "To the best of our knowledge, we have described for the first time the implication of PIWIL3 and PIWIL4 in cell motility through EMT modulation of tumor and non-tumor pancreatic cells." (PMID 32357464, 2020). "Our experiments, designed to evaluate cell motility, chemoresistance and undifferentiated phenotype, revealed that the effect observed after PIWIL3 and/or PIWIL4 downregulation in tumor cells were also shown by the non-tumor cell line." (PMID 32357464, 2020). "We also observed that PIWIL3 and/or PIWIL4 silencing impaired undifferentiated phenotype and enhanced drug toxicity in both tumor- and non-tumor-derived cell lines." (PMID 32357464, 2020).
benign tumors (1 paper, 2020). "Most tumors had no PIWIL3 expression whereas PIWIL4 had significantly lower expression in early stage HGSOC samples but not late stage when compared to benign tumors." (PMID 33374923, 2020).
pancreas (1 paper, 2020). "A second profile of expression associated variable PIWIL2 and PIWIL4 genes downregulation, an aberrant level of PIWIL1 and absence of PIWIL3 expression observed in anal canal, head and neck, cervix, skin, kidney and pancreas tumors." (PMID 33008024, 2020).
PIWIL3 also shares sentences with these, for which no sentence is quoted: Azoospermia (2 papers); colon cancer (1); hepatocellular carcinoma (1); non-small cell lung carcinoma (1); Premature ovarian insufficiency (1).